SOX10 (SRY-box transcription factor 10)
Diseases named in the same sentence as SOX10 in open-access papers (continued):
Sharing a sentence is not in itself a finding about the gene and the disease.
tumor (374 papers, 2009 to 2026). "The interplay of these factors contributes to the intricate SOX10‐mediated MITF regulation underlying tumor heterogeneity." (PMID 40458894, 2025). "We construct two evaluation sets: tumour-associated markers (MelanA, S100, gp100, SOX10) and lymphocyte markers (CD20, CD3, CD8a)." (PMID 40842484, 2025). "SOX10 loss reduces proliferation but promotes tumor invasiveness and resistance to BRAF and/or MEK inhibitors." (PMID 40866912, 2025). "In prior work in both zebrafish and mice, loss of sox10 is clearly associated with a loss of tumor-initiating potential and cell proliferation." (PMID 40879132, 2025). "Consistent with the DepMap prediction, sox10 inactivation markedly reduced tumor incidence, which likely reflects loss of proliferation." (PMID 40879132, 2025). "For example, SOX10 is well known for its role in neural crest development and has been implicated in the promotion of tumor metastasis, suggesting a shift toward a more migratory and invasive phenotype during relapse." (PMID 41238550, 2025). "Research indicates that predictive models, constructed from gene expression disparities linked to SOX10, and risk scores assessing the tumor immune microenvironment, which can guide clinical immunotherapy." (PMID 40342816, 2025). "SOX10 expression promotes proliferation and tumor growth, whereas its loss is sufficient to induce an invasive, slow-cycling state." (PMID 41193428, 2025). "The results confirm these tumor types’ distinct pathogenesis and nature and highlight SOX-10 as a valuable diagnostic marker." (PMID 39684268, 2024). "The loss of SOX-10 function leads to a significant decrease in survival, increasing tumor invasiveness and immune cell infiltration." (PMID 36005160, 2022). "SOX10 IHC, as a sensitive and specific method of assessing melanocyte loss, has the potential to be a surrogate marker for tumor immune response." (PMID 34287276, 2021). "Here the authors perform an integrative analysis of these subtypes resulting in the identification of SOX10 whose loss induces a mesenchymal phenotype and promotes tumour progression." (PMID 33339831, 2020). "We further show, using a recently described immunocompetent syngeneic mouse model that SOX10 loss leads to a dramatic decrease in survival, increased tumour invasion and immune cell infiltration." (PMID 33339831, 2020). "Sry-related HMG-box gene 10 (SOX10) has been implicated in tumor progression in various malignancies, but its functional role and underlying mechanism in TNBC remain unclear." (PMID 42232539, 2026). "Overexpression of cytoplasmic and perinuclear SOX10 may indicate its inactive form, mutated, or interacting with other proteins, such as nestin, and therefore, playing a role of greater tumor aggressiveness in oral canine melanomas." (PMID 41012776, 2025). "Notably, CD8+ T cell and SOX10+ tumor cell colocalization was associated with improved PFS indicating the importance of tumor-immune cell interaction for effective anti-tumor activity." (PMID 41282765, 2025). "We therefore explored A-485 effects on the MAPKi-resistant cell lines WM983B BRAFi-R (partial loss of SOX10) and SK-Mel-28 BRAFi-R (SOX10 undetectable) to determine whether A-485 could effectively inhibit tumor cell growth in this setting." (PMID 38994683, 2024). "SOX10 has been shown to be expressed in TNBCs, and is associated with worse clinical outcomes in these patients, highlighting the similarities between this tumor subtype and the low-ER tumors in our study." (PMID 36859337, 2023). "The purpose of this study is to determine SOX10 expression in TNBC, its association with tumor grade for molecular categorization, and to determine the diagnostic significance of SOX10 in TNBC at the metastatic site in the case of an unknown primary." (PMID 36120242, 2022). "We therefore asked whether the increase in SOX10 observed in white matter may also play a causal role in the induction of tumour cell differentiation." (PMID 33846316, 2021).
tumor (continued). "In agreement with the RNA expression data, quantification of Aif1 staining showed an increase in tumour-associated macrophage infiltration in the SOX10 KD tumours (Aif1 positive area: NT: 4.57%; SOX10 KD: 17.11%; 10 fields of view in 3 tumours in each condition; P < 0.001)." (PMID 33339831, 2020). "Notably, loss of SOX10 has also been linked to adverse outcomes in other neural crest-derived tumours." (PMID 33339831, 2020). "Finally, we returned to our primary tumour data to find evidence of SOX10-associated RTK I-to-MES transition in the RTK I and MES patient samples." (PMID 33339831, 2020). "A single-allele deletion in the Sox10 gene could significantly delay tumor development in a mouse model." (PMID 31013830, 2019). "In addition, SOX10 is associated with developmental plasticity and bipotent progenitor identity in fetal mammary stem cells, suggesting that the activity of this transcription factor reflects the reactivation of the bipotent progenitor program in tumor cells." (PMID 36859337, 2023). "Notably, NRASQ61K-associated tumor progression was associated with an increase in SOX10 expression." (PMID 25629959, 2015). "Our computational analysis suggests that SOX10 depletion in UM reshapes the miRNA regulatory landscape in a manner potentially consistent with tumor-suppressive activity, requiring experimental validation." (PMID 42120529, 2026). "Epigenetic alterations, including DNA methylation, chromatin remodeling, non-coding RNAs, and SOX10 dysfunction, further shape tumor behavior." (PMID 42143176, 2026). "In PCC organoids, SOX10 positivity—likely reflecting sustentacular-derived progenitors—suggests a role for these cells in tumor development." (PMID 40576438, 2025). "Specifically, this network suppresses DIRC3 transcription, which in turn regulates chromatin accessibility to limit SOX10 and maintain expression of tumour-suppressive genes such as IGFBP5." (PMID 41463281, 2025). "Based on the SOX10 marker and the nuclear morphology, the domain expert concluded that cells c and d were tumor cells." (PMID 39255170, 2025). "Immunohistochemistry revealed diffuse and strong positivity for SOX10 in tumor cells, consistent with metastatic spindle cell melanoma." (PMID 40290795, 2025). "Immunohistochemical staining revealed that the tumor cells were positive for S100 and SOX10, and showed focal positivity for cytokeratin AE1/AE3 and cytokeratin OSCAR." (PMID 41384184, 2025). "Focal tumor nests were surrounded by a layer of myoepithelial cells highlighted by p63 and SOX10, supportive of an in situ component within sweat glands." (PMID 41143220, 2025). "Here, we focus on SOX10's role in miRNA‐mediated network motifs, detailing their impact on tumor cell growth, proliferation, and migration." (PMID 40458894, 2025). "This procedure included isolating nuclei from the tumors and flow sorting them by ploidy (using DAPI staining) and markers of tumor origin (SOX10 or S100)." (PMID 40004220, 2025). "By this definition, we found that QCCs represented 12% of all SOX10+ tumor cells, with the proportion varying from one tumor domain to the next." (PMID 41473281, 2025). "Averaged across the five tumor domains, ~58% of cells were SOX10+ tumor cells whereas 42% were lymphocytes, myeloid cells, and stromal cells of various types." (PMID 41473281, 2025). "In our patient, the tumor exhibited a spindle cell morphology with necrosis, accompanied by diffuse strong S100 and patchy SOX10 expression." (PMID 41384184, 2025). "We generated two compounds, OPN-9652 and OPN-9643, that inhibit TEADs, resensitize SOX10 KO cells to BRAFi + MEKi, and delay the onset of tumor resistance to BRAFi + MEKi from MRD." (PMID 41193428, 2025). "All tumor cells were immunopositive for S100 and SOX10, and all but one cases stained with the CK7 antibody." (PMID 40033554, 2025).
tumor (continued). "Considering dyNF-like tumors, we identified two dyNF types, where tumor cells (TCs) were S100B+/SOX10+ (dyNF S100b+ type) or S100B−/SOX10+ (dyNF S100b− type)." (PMID 41223283, 2025). "Noteworthy findings included enhanced regulon activities of SOX10, which plays an essential role in tumor proliferation, migration, and apoptosis." (PMID 39670859, 2025). "Histological assessment typically demonstrates tumor cells featuring prominent nucleoli and melanin granules, while immunohistochemical staining is positive for S100, Melan-A, and SOX10." (PMID 41142597, 2025). "On immunohistochemistry, diffuse and strong nuclear and cytoplasmic positivity of S100, along with extensive SOX10 positivity, confirmed the neural crest origin of the tumour." (PMID 40255781, 2025). "Immunohistochemical staining demonstrated diffuse glial fibrillary acidic protein (GFAP) positivity and S100 expression, with strong SOX10 nuclear labeling in tumor cells." (PMID 41458616, 2025). "This is consistent with the presence of an MPI = −1 state in approximately 20% of SOX10+ tumor cells." (PMID 41473281, 2025). "Enrichment analysis was conducted on the co-expressed genes of SOX10 and the differentially expressed genes in tumor tissues of low- and high- SOX10 expression groups." (PMID 40342816, 2025). "Immunohistochemical analysis revealed that the tumor cells in both components were diffusely positive for S-100 and SOX-10." (PMID 40255822, 2025). "SOX10 was highly expressed in the skin and eye in the interactive body map, in accordance with the preferred areas of tumor." (PMID 40342816, 2025). "These included tumour markers (MelanA, S100, gp100, SOX10), immune markers (CD3, CD8a, CD20, CD16, CD31) and antigen-presentation markers (HLA-ABC, HLA-DR)." (PMID 40842484, 2025). "After proteins of interest were identified, we switched to the detailed line chart views to measure SOX10 (a tumor marker) and CD3D (immune marker), HLAA (marking cell membrane), along with inhibitory pathway PDL1-PD1." (PMID 39255170, 2025). "The tumor cells showed strong positivity for SOX10 (20× magnification) and S100, confirming neural crest origin." (PMID 40361436, 2025). "PRRX1-NCOA1-rearranged fibroblastic tumor: These tumors exhibit pigmentation and S100 positivity but are Sox10-positive and harbor PRRX1-NCOA1 fusion." (PMID 41409361, 2025). "(i) Differential sensitivity to SOX10: Tumor cells with varying SOX10 expression levels exhibit unique responses, leading to distinct changes in MITF expression, particularly under nonlinear regulation." (PMID 40458894, 2025). "These panels include key markers, such as SOX10 for tumours, HLA-DR for antigen presentation and CD3/CD8a for T cell profiling, which are shared with the generated protein multiplex." (PMID 40842484, 2025). "Here, we developed a refined ploidy-based flow-sorting method that enriches SOX10- or S100-labelled tumor nuclei before genomic profiling." (PMID 40004220, 2025). "Upregulation of Notch target genes was also observed upon SOX10-KD in both mouse and human patient-derived tumor spheres (Fig. EV4A)." (PMID 39285246, 2024). "The following main research directions were observed: angiogenesis factors, IgG4, pro-inflammatory molecules, oxidative stress, cell surface, and adhesion molecules, tumor stem cells, cytokines and lymphocytes, SOX-10, proteomic analysis, and others." (PMID 39684268, 2024). "The study also introduces a new observation in tumor cells’ pattern and underscores the value of the Sox10 marker in diagnosing PNSTs in cats, offering new insights for veterinary pathologists." (PMID 38612342, 2024). "Detailed immunohistological investigations have allowed for the assessment of specific marker expressions such as Ki-67, CK19, SOX10, and vimentin to validate the tumor microenvironment relevance of the model." (PMID 39329875, 2024). "We next used the Sox10-KD cell model to investigate the targeting of the slow-cycling qNSC-like tumor cells." (PMID 39285246, 2024).
tumor (continued). "On immunohistochemistry, the tumor cells were positive for S100P and SOX-10 and focally positive for HMB-45 and Melan A. Tumor cells were negative for CK, EMA, SMA, TTF1, PAX8, GATA3 and SALL4." (PMID 38509523, 2024). "This highlights a discrepancy in SOX10+ versus OLIG2+ tumor cells, especially considering that Sox10 is transcriptionally regulated by OLIG2 within OPCs40." (PMID 39609428, 2024). "We next analyzed SOX10 intra-tumor heterogeneity in these ZEB1high tumors and evidenced cell populations with decreased SOX10 intensity." (PMID 38519642, 2024). "The tumour cells were diffusely and intensely positive for multiple melanocytic markers: MelanA, S100, SOX10, and PRAME." (PMID 39001214, 2024). "Immunohistochemical study showed a predominantly myoepithelial tumor cell population with expression of S-100, SOX-10, p40, p63, SMA and Pan cytokeratin (AE1/AE3)." (PMID 39319059, 2024). "Single-cell transcriptome profiling of Sox10-KD tumors indicates that Sox10 suppression is sufficient to induce tumor progression to an aggressive NSC/developmental-like phenotype, including a quiescent NSC-like cell population." (PMID 39285246, 2024). "In this study, tumor cells exhibited diffuse strong positivity in 98 cases (99%) for S100, 97 cases (98%) for SOX10, and 97 cases (98%) for Vimentin." (PMID 39158355, 2024). "Efforts to therapeutically target SOX10 have been challenging due to the relative inaccessibility of targeted therapies to transcription factors and specific complexities associated with loss of SOX10 activity, which may promote tumor cell invasion and metastasis under certain circumstances." (PMID 38994683, 2024). "In prior literature, implicated overlapping genes, including WASF3, EDNRB, SOX10, BAMBI have been implicated in processes including tumor progression, migration, and invasion." (PMID 38857306, 2024). "In our patient, we observed that tumour cells expressed SOX10 and S-100 protein, which confirmed that the tumour was intercalated duct differentiation." (PMID 38982505, 2024). "(c) Immunohistochemical (IHC) with diaminobenzidine (DAB) showing tumor (SOX10) and TILs (CD3) within a liver metastasis, (d, e) corresponding analysis of 4-1BB+ TILs in a section, (d) and in image analysis comparing both treatments (e)." (PMID 39312285, 2024). "The tumor cells were diffusely positive for S100, SOX10, and cytokeratins 7, 18, and 19, in both the luminal and abluminal cells." (PMID 37415052, 2023). "In cells classified as tumor cells, the strongest gradients were traced back to the images of MelanA and SOX10, whereas for HEVs it was in the images of CD31 and PNAd." (PMID 37463931, 2023). "HE staining presented spindle-shaped tumor cells with mitoses and IHC staining positivity for SOX10." (PMID 36710341, 2023). "The immunohistochemistry analysis of the right plantar tumor showed diffuse positivity for SOX-10, HMB45, Melan-A, with weak S100 positivity in certain areas." (PMID 37352079, 2023). "On the other hand, SOX10 appears to have a more direct correlation to low-ER tumors, with high (> 10% of tumor cells) expression of SOX10 observed in 47.47% of low-ER tumors, while only 1 of the luminal B tumors (4.76%) expressed high levels of SOX10." (PMID 36859337, 2023). "This localization is exceptionally rare, but it can pose significant diagnostic challenges as rare cases of intraepidermal involvement have been reported, and the tumor cells are positive for melanocytic markers such as S100, SOX10, HMB45, MelanA, or MiTF." (PMID 37373134, 2023).
tumor (continued). "Immunohistochemically, the tumor cells stained diffusely positive for S100 protein and SOX10, indicating Schwann cell differentiation, and MIB1-positive cells showed an increase of up to 10% in the tumor center." (PMID 39516973, 2023). "The lymphoid biomarker panel depicts CD3+ T cells, CD3+CD8+ cytotoxic T cells, and CD3+FOXP3+ regulatory T cells (Tregs), while the myeloid biomarker panel shows CD68+ macrophages; the tumor cells were stained for PanCK/SOX10." (PMID 36900182, 2023). "Immunohistochemistry analysis showed that the tumor cells were positive to various extents for S100, SOX10, MelanA, HMB45, MiTF, and tyrosinase." (PMID 37373134, 2023). "We also observed a moderate positive correlation between the visually estimated percentage tumor nuclei (generally >60%) and the computer-assisted SOX10+ cell density quantitation (generally 10–60%)." (PMID 35058553, 2022). "We postulate that progressive erosion of the epigenome in SOX10+ tumour-initiating cells simulates these conditions, driving NCSC-like reprogramming and poor clinical outcomes in SOX10 + TNBCs." (PMID 35501337, 2022). "The strong and diffuse expression of S100 protein and SOX10, along with the retained expression of H3K27me3 in tumor cells, are helpful to exclude a malignant peripheral nerve sheath tumor." (PMID 35741273, 2022). "An immunohistochemical (IHC) panel inclusive of p63, SOX-10, S-100, calponin, vimentin, and Ki-67 was done to evaluate the tumour and grade PAC." (PMID 35505695, 2022). "In fact, the low levels of OLIG2 and SOX10 immunostaining seen in this tumor are more consistent with what has been reported for subepenymomas." (PMID 35484611, 2022). "In tumours, nuclear SOX10 was almost exclusive to TNBC, and predicted poorer outcome amongst cross-sectional (p = 0.0015, hazard ratio 2.02, n = 224) and metaplastic (p = 0.04, n = 66) cases." (PMID 35501337, 2022). "Tumor distribution of PXN and Sox-10 were variable across the fields of view (FOV) within the same tumor and between normal nerve fibers." (PMID 36669002, 2022). "Strikingly, we discovered that while COL11A1 expression in the latter is nearly restricted to CAFsCOL11A1 in their vicinity, SOX10 + tumours produce COL11A1 in the tumour cells at varying rates." (PMID 34378164, 2022). "In MM for example, gain in ATF1 and SOX10, associated with loss of TFAP2A expression, drive tumor growth and metastasis by regulating, in an opposing manner, a number of genes involved in cell adhesion, extracellular matrix remodeling, and cell survival." (PMID 35477713, 2022). "The top downregulated genes [WIF1, DACT2, ID4, TP63, SOX10] in tumours in our transcriptomic profile were regulators of Wnt signalling, cell differentiation and morphogenesis and acted as inhibitors of tumour growth in BC31–34." (PMID 34997107, 2022). "Consistent with functional analysis of Sox10 in experimental mice, our human tumour network studies show that SOX10’s TNBC-specific regulatory module confers similarity to highly plastic NCSCs." (PMID 35501337, 2022). "When developing THRRed, repetitive errors were also observed; that is, unspecific SOX10 reactions unrelated to tumor nuclei." (PMID 36361209, 2022). "A subset of cells stained positive for OLIG2 and SOX10, with approximately 20% of cells staining positive for each of these markers in some areas of the tumor." (PMID 35484611, 2022). "The tumor showed positivity for SOX10, S100, and Melan-A and intensely expressed HMB45 in the pleomorphic component." (PMID 36289768, 2022). "Immunohistochemical staining showed that S-100 protein was diffusely expressed in tumor cells in all cases and SOX-10 protein was positive in some cases." (PMID 35959130, 2022). "Yet, due to low or missing tumor-cell SOX10 positivity, advantages of the annotation technique were limited in lymph-node and organ metastases." (PMID 36361209, 2022).